ERFL (ETS repressor factor like)
Synonyms: erfl1
Gene: Protein-coding gene on chromosome 19 (41,907,704 to 41,928,449, reverse strand). Ensembl gene ENSG00000268041.
Subcellular location: Nucleus
Subcellular location (Human Protein Atlas): Nucleoli; Nucleoplasm; Cytosol
Gene Ontology:
Molecular function: DNA-binding transcription factor activity, RNA polymerase II-specific; DNA-binding transcription factor activity; sequence-specific DNA binding
Biological process: cell differentiation; regulation of transcription by RNA polymerase II; regulation of DNA-templated transcription
Cellular component: nucleus
Genetic constraint (gnomAD): Loss-of-function variants: 8 observed, 23.95 expected, observed/expected ratio (o/e) 0.33, 90% interval 0.19 to 0.6. The upper end of that interval is the gene's LOEUF score, 0.6, which puts it in group 2 of 6, group 1 being the genes least tolerant of losing a copy. Missense variants: 290 observed, 383.67 expected, observed/expected ratio (o/e) 0.76, 90% interval 0.69 to 0.83. Synonymous variants: 172 observed, 176.38 expected, observed/expected ratio (o/e) 0.98, 90% interval 0.86 to 1.11.
Homologues: Orthologues: chimpanzee ERFL (99% identical), dog ERFL (95% identical), rat Erfl (93% identical), mouse Erfl (93% identical), pig ERFL (93% identical), zebrafish si:ch211-265g22.4 (21% identical). Paralogues in human: ERF (46% identical), ETV3L (36% identical), ETV3 (36% identical), FLI1 (21% identical), ELK4 (21% identical), ERG (21% identical), ELK1 (20% identical), ELK3 (19% identical), ETS1 (19% identical), ETS2 (19% identical), ELF4 (18% identical), FEV (18% identical), and 16 more.